TMEM115 (transmembrane protein 115)
Description:
May play a role in retrograde transport of proteins from the Golgi to the endoplasmic reticulum. May indirectly play a role in protein glycosylation in the Golgi.
Synonyms: PL6
Tractability: Antibody: UniProt predicts a signal peptide or a membrane-spanning region. PROTAC: ubiquitination databases record sites on it; its protein half-life has been measured.
Gene: Protein-coding gene on chromosome 3 (50,354,749 to 50,359,521, reverse strand). Ensembl gene ENSG00000126062.
Subcellular location: Golgi apparatus, Golgi stack membrane
Subcellular location (Human Protein Atlas): Golgi apparatus
Pathways (Reactome):
Vesicle-mediated transport: COPI-mediated anterograde transport
Gene Ontology:
Molecular function: identical protein binding; protein binding
Biological process: retrograde vesicle-mediated transport, Golgi to endoplasmic reticulum; negative regulation of cell population proliferation
Cellular component: Golgi apparatus; Golgi cisterna membrane; Golgi transport complex; nucleus; Golgi membrane; membrane
Genetic constraint (gnomAD): Loss-of-function variants: 8 observed, 21.12 expected, observed/expected ratio (o/e) 0.38, 90% interval 0.22 to 0.68. The upper end of that interval is the gene's LOEUF score, 0.68, which puts it in group 2 of 6, group 1 being the genes least tolerant of losing a copy. Missense variants: 374 observed, 469.64 expected, observed/expected ratio (o/e) 0.8, 90% interval 0.73 to 0.87. Synonymous variants: 229 observed, 212.21 expected, observed/expected ratio (o/e) 1.08, 90% interval 0.97 to 1.2.
Homologues: Orthologues: chimpanzee TMEM115 (99% identical), macaque TMEM115 (99% identical), dog TMEM115 (97% identical), guinea pig TMEM115 (96% identical), rat Tmem115 (96% identical), rabbit TMEM115 (94% identical), mouse Tmem115 (94% identical), pig TMEM115 (87% identical), zebrafish tmem115 (68% identical), tropical clawed frog tmem115 (51% identical), Drosophila melanogaster CG9536 (37% identical), Caenorhabditis elegans F11A10.6 (23% identical).
Diseases named in the same sentence as TMEM115 in open-access papers:
TMEM115 is named in the same sentence as 11 diseases in open-access papers, as found by Europe PMC text mining. Sharing a sentence is not in itself a finding about the gene and the disease. The quoted sentences say what the papers report.
breast carcinoma (2 papers, 2014 to 2022). "The TMEM115 expression profile in cancer cell lines shows that TMEM115 seems to be expressed at a higher level in invasive breast cancer cells, such as MDA-MB-231 and Hs578T; as compared to MCF7, a weakly invasive breast cancer cell line." (PMID 24806965, 2014). "TMEM115 is ubiquitously expressed as a protein of ∼35 kDa in the examined cell lines; with the highest expression level in MDA-MB-231 and Hs578t, both of which are invasive breast cancer cells." (PMID 24806965, 2014).
astrocytoma (1 paper, 2025). "Furthermore, given the new definition of adult gliomas in the 2021 WHO classification, we investigated the expression of TMEM115 in IDH mutation astrocytoma, IDH mutation, and 1p19q codeletion oligodendroglioma, and IDH wild-type glioblastoma (P < 0.05)." (PMID 40552281, 2025).
glioblastoma (1 paper, 2025). The most malignant astrocytic tumor (WHO grade IV). "The significant upregulation of TMEM115 expression in IDH wild-type glioblastoma." (PMID 40552281, 2025).
glioma (1 paper, 2025). A benign or malignant brain and spinal cord tumor that arises from glial cells (astrocytes, oligodendrocytes, ependymal cells). "We used bioinformatics to explore the association between TMEM115 mRNA expression, glioma patients’ prognosis, and its relationship with clinicopathologic features." (PMID 40552281, 2025). "In the multivariate analysis, TMEM115 protein expression (HR = 1.840, P = 0.001), age (HR = 1.522, P = 0.019), and grade (HR = 2.066, P < 0.001) were independently associated with 5-year OS in glioma patients." (PMID 40552281, 2025). "Further analysis confirmed TMEM115 levels as a potential indicator for assessing glioma patient survival." (PMID 40552281, 2025). "First, further evidence of the role of TMEM115 in glioma progression and macrophage polarization using animal models is needed." (PMID 40552281, 2025). "In this study, we employed multicolor mIHC and InForm to assess TMEM115 protein expression within the TME based on glioma tissue microarrays (TMAs) alongside patients’ clinical data." (PMID 40552281, 2025). "Survival analyses demonstrated that high TMEM115 levels led to poorer OS in glioma patients (HR = 2.51, P < 0.001)." (PMID 40552281, 2025). "Given the limitations of predicting protein expression only based on transcription levels, we conducted mIHC staining of glioma TMA sections to assess TMEM115 protein expression and localization." (PMID 40552281, 2025). "TMEM115 was found to be highly expressed in glioma tissues and to affect the prognostic survival of glioma patients, influencing the progression of gliomas." (PMID 40552281, 2025). "In glioma patients, elevated TMEM115 expression was strongly correlated with adverse prognosis (HR = 1.9, P < 0.05; HR = 1.6, P < 0.05)." (PMID 40552281, 2025). "Correlation of TMEM115 protein expression with clinicopathological characteristics in glioma patients." (PMID 40552281, 2025). "Future research endeavors ought to be directed toward confirming the functional mechanisms of TMEM115 in gliomas and delving deeper into its therapeutic potential within the realm of immunotherapy." (PMID 40552281, 2025). "RNA-seq data from The Cancer Genome Atlas and Chinese Glioma Genome Atlas databases of glioma patients and multiplex Immunohistochemistry by glioma tissue microarrays were analyzed to determine the expression and localization of TMEM115." (PMID 40552281, 2025). "The optimal cut-off value for TMEM115 protein expression in gliomas was determined based on the OS of glioma patients and categorized into high and low-expression groups." (PMID 40552281, 2025). "To elucidate the effect of TMEM115 on glioma phenotype and to determine its oncogenic role, we designed and established shRNAs and their respective lentiviral systems." (PMID 40552281, 2025). "To verify this, we performed mIHC staining and analyzed the expression of TMEM115 protein in the glioma TME using Pearson’s test." (PMID 40552281, 2025). "In this study, we investigated the relationship between TMEM115 protein expression and TAMs as well as immune checkpoints in glioma TMAs." (PMID 40552281, 2025). "These suggest the clinical significance of TMEM115 and its potential utility as a prognostic biomarker for glioma patients." (PMID 40552281, 2025). "Further analysis confirmed a correlation between TMEM115 protein expression in glioma tissues, World Health Organization Grade, and patients’ poorer prognosis." (PMID 40552281, 2025). "However, the role of TMEM115 in glioma progression is still unclear and, therefore, needs further exploration." (PMID 40552281, 2025). "Collectively, these findings support TMEM115 as a potential indicator for glioma patient survival." (PMID 40552281, 2025). "In summary, this is a report of TMEM115 expression in glioma patients." (PMID 40552281, 2025). "TMEM115 protein was found to be primarily localized in glioma cells plasma membrane." (PMID 40552281, 2025).
glioma (continued). "We observed a correlation between TMEM115 and WHO grade, with elevated expression linked to a poorer prognosis, leading us to hypothesize that TMEM115 potentially plays a role in glioma progression, thereby influencing tumor growth." (PMID 40552281, 2025). "In addition, these results elucidate the relationship between TMEM115 expression and the expression of macrophages and common immune checkpoints in gliomas." (PMID 40552281, 2025). "Upon validation, we examined the effect of TMEM115 on glioma cell phenotype." (PMID 40552281, 2025). "Although previous studies have reported elevated mRNA levels of TMEM115 in glioma compared to benign tissues, with implications for poorer patient survival, current literature indicates a poor correlation between mRNA and protein levels, and their expression can be inconsistent." (PMID 40552281, 2025). "Additionally, the proliferation, migration, and invasion of glioma cells were decreased when TMEM115 expression was downregulated." (PMID 40552281, 2025). "Moreover, mIHC results demonstrated predominant TMEM115 protein expression on the plasma membrane of both glioma and benign non-glioma cells, with varying degrees of expression." (PMID 40552281, 2025). "Furthermore, we established a correlation between TMEM115 protein levels and the degree of glioma malignancy and TME using mIHC." (PMID 40552281, 2025). "We hypothesized that TMEM115 and M2 macrophages promote glioma cell growth and influence their biological behavior." (PMID 40552281, 2025). "In summary, TMEM115 could be a promising prognostic marker and a potential target for glioma immunotherapy." (PMID 40552281, 2025). "Thus, the effects of TMEM115 on glioma proliferation, migration, and invasion were demonstrated." (PMID 40552281, 2025). "Hence, our present research was initiated to determine whether TMEM115 could serve as a promising biomarker for glioma treatment." (PMID 40552281, 2025). "The results showed a significant increase in TMEM115 mRNA expression in glioma tissues compared to nonmalignant brain tissues (P < 0.05)." (PMID 40552281, 2025). "The results revealed a significant increase in TMEM115 expression in tumors than in non-tumor brain tissues, and knockdown of TMEM115 affects the ability of glioma cell lines to proliferate, migrate, and invade." (PMID 40552281, 2025). "Our preliminary analysis utilizing the TCGA database revealed a significant increase in Transmembrane protein 115 (TMEM115) mRNA expression in glioma tissues regarding non-glioma samples, with implications for patient outcomes." (PMID 40552281, 2025).
renal clear cell carcinomas (1 paper, 2014). "TMEM115 has been reported to have reduced expression in renal clear cell carcinomas and other VHL-deficient tumors and to exhibit Golgi localization." (PMID 24806965, 2014). "However, by contrast, it has been reported that there is a loss of TMEM115 expression in renal clear cell carcinomas and other VHL-deficient tumors." (PMID 24806965, 2014).
tumor (5 papers, 2010 to 2025). "Pearson’s test was utilized to evaluate the association between TMEM115 protein levels, tumor immune infiltrating cells, and immune checkpoints." (PMID 40552281, 2025). "We found that TMEM115 protein levels in tumor tissues were positively associated with CD68+ (R = 0.283, P < 0.001) and CD68+CD163+ (R = 0.145, P = 0.046) macrophages." (PMID 40552281, 2025). "This is because high TMEM115 and PD-L1 expression implies tumor reliance on the PD-L1 pathway for immune evasion." (PMID 40552281, 2025). "Since immune checkpoints can fuel tumor immunotherapy, we also evaluated the correlation of TMEM115 with the common immune checkpoints, the results showed that TMEM115 was correlations with CD274 (PD-L1) (R = 0.15, P = 2.7e-11)." (PMID 40552281, 2025). "TMEM115, also known as PL6, located on chromosome 3p21.3, was originally thought to function as a tumor suppressor." (PMID 24806965, 2014). "As anticipated, TMEM115 mRNA levels were found to be elevated in tumor than non-tumor samples." (PMID 40552281, 2025). "Consistent with mRNA levels, elevated levels of TMEM115 were observed in tumor tissues." (PMID 40552281, 2025). "Importantly, the protein levels were consistent with mRNA expression, exhibiting significantly increased expression in tumor tissues with high TMEM115 expression." (PMID 40552281, 2025).
infection (1 paper, 2025). The state of being infected such as from the introduction of a foreign agent such as serum, vaccine, antigenic substance or organism. "The U87MG and U251 cell lines, which are relatively malignant, were selected to be infected with shRNAs, firstly, using lentiviral infection to generate stable knockdown cell lines, thus promoting the knockdown of TMEM115." (PMID 40552281, 2025).
TMEM115 also shares sentences with these, for which no sentence is quoted: cancer (1 paper); lung carcinoma (1); metastatic cancer (1); oligodendroglioma (1).